PCF11 (PCF11 cleavage and polyadenylation factor subunit)
Description:
Component of pre-mRNA cleavage complex II, which promotes transcription termination by RNA polymerase II.
Synonyms: KIAA0824
Tractability: PROTAC: UniProt records ubiquitination sites on it; ubiquitination databases record sites on it; its protein half-life has been measured.
Gene: Protein-coding gene on chromosome 11 (83,156,988 to 83,187,451, forward strand). Ensembl gene ENSG00000165494.
Subcellular location: Nucleus
Subcellular location (Human Protein Atlas): Nucleoplasm; Mitochondria
Pathways (Reactome):
Metabolism of RNA: Processing of Intronless Pre-mRNAs; mRNA 3'-end processing; mRNA Polyadenylation
Gene expression (Transcription): RNA Polymerase II Transcription Termination; RNA polymerase II transcribes snRNA genes
Disease: Dengue Virus-Host Interactions
Gene Ontology:
Molecular function: protein binding; RNA polymerase II complex binding; mRNA binding
Biological process: regulation of mRNA 3'-end processing; termination of RNA polymerase II transcription; co-transcriptional mRNA 3'-end processing, cleavage and polyadenylation pathway; mRNA 3'-end processing
Cellular component: mRNA cleavage factor complex; nucleoplasm; nucleus
Genetic constraint (gnomAD): Loss-of-function variants: 7 observed, 117.68 expected, observed/expected ratio (o/e) 0.0595, 90% interval 0.033 to 0.11. The upper end of that interval is the gene's LOEUF score, 0.11, which puts it in group 1 of 6, group 1 being the genes least tolerant of losing a copy. Missense variants: 1,337 observed, 1,546.3 expected, observed/expected ratio (o/e) 0.86, 90% interval 0.83 to 0.9. Synonymous variants: 525 observed, 551.11 expected, observed/expected ratio (o/e) 0.95, 90% interval 0.89 to 1.02.
Homologues: Orthologues: chimpanzee PCF11 (99% identical), rabbit PCF11 (96% identical), macaque PCF11 (94% identical), rat Pcf11 (94% identical), dog PCF11 (90% identical), pig PCF11 (89% identical), guinea pig PCF11 (88% identical), mouse Pcf11 (86% identical), tropical clawed frog pcf11 (56% identical), zebrafish pcf11 (38% identical), Drosophila melanogaster Pcf11 (22% identical), Caenorhabditis elegans pcf-11 (14% identical).
Diseases named in the same sentence as PCF11 in open-access papers:
PCF11 is named in the same sentence as 12 diseases in open-access papers, as found by Europe PMC text mining. Sharing a sentence is not in itself a finding about the gene and the disease. The quoted sentences say what the papers report.
neuroblastoma (8 papers, 2018 to 2025). Neuroblastoma (NB) is the most common solid, extracranial childhood tumor. "In neuroblastoma, high levels of PCF11 regulate differentiation, proliferation, apoptosis and cell cycle, while low levels of PCF11 are associated with favorable outcomes and spontaneous tumor regression." (PMID 35756640, 2022). "Postnatal down-regulation of PCF11 induces neurodifferentiation and a low expression of PCF11 is associated with a favorable outcome and spontaneous tumor regression in such neuroblastomas." (PMID 33526057, 2021). "Postnatal PCF11 down-regulation induces a neurodifferentiation program, and low-level PCF11 in neuroblastoma associates with favourable outcome and spontaneous tumour regression." (PMID 30552333, 2018). "In light of PCF11 controlling APA of a module of transcripts associated with neurodifferentiation, we speculated that the expression of PCF11 may be associated with spontaneous neuroblastoma regression." (PMID 30552333, 2018). "Depletion of PCF11 in human neuroblastoma cell lines, abolished colony formation, induced retarded tumor growth and reduced invasiveness." (PMID 35756640, 2022). "Studies have reported that PCF11 induces invasiveness in neuroblastoma through mediating WNT signaling via beta-catenin 1 (CTNNB1), subsequently activating PI3K/AKT that regulates, cell cycle progression, proliferation and apoptosis." (PMID 35756640, 2022). "In an extensive screen of potential CPA effectors in neuroblastoma cells PCF11 emerged as a critical regulator of APA." (PMID 32560344, 2020). "Significantly, in neuroblastoma low-level PCF11 expression, significantly fewer adverse outcomes and spontaneous tumour regression are observed, suggesting dysregulated APA can mimic oncogenic mutational events." (PMID 32560344, 2020). "They establish PCF11 as a critical regulator of neurogenesis with aberrant PCF11 causing pervasive (de)regulation of APA bearing detrimental consequences for normal neurodifferentiation and a functional role in neuroblastoma tumorigenesis." (PMID 30552333, 2018). "When comparing stage 4S with stage 4 neuroblastomas, we identified a significantly higher PCF11 expression in the latter (p-value = 1.15 × 10−6)." (PMID 30552333, 2018). "Here, the authors discover extensive transcriptome 3′end-alterations in neuroblastoma, regulated by PCF11, and provide an interactive data repository of transcriptome-wide alternative polyadenylation." (PMID 30552333, 2018). "Neuronal PCF11 expression drops around birth and during neuronal differentiation, but appears to be high in neuroblastomas and, interestingly, other paediatric cancer entities with embryonic origin." (PMID 30552333, 2018). "PCF11 regulates vertebrate development, and differentiation in neuroblastoma." (PMID 35756640, 2022). "Moreover, PCF11 expression levels are predictive of clinical outcomes of neuroblastoma patients, suggesting that PCF11 has relevance to human pathology." (PMID 30819644, 2019). "Indeed, depletion of PCF11 abolished colony formation, reduced cell invasiveness and resulted in retarded tumour growth in a neuroblastoma xenograft model." (PMID 30552333, 2018). "In addition, some of the observed changes upon PCF11 depletion (i.e. activation of the PI3K/Akt pathway) are surprisingly consistent with their reported role for neuroblastoma differentiation." (PMID 30552333, 2018). "While in BC, PCF11 is part of the MAPK/ERK pathway, it is part of the WNT/PI3K/AKT signaling pathway in neuroblastoma." (PMID 35756640, 2022). "After neuroblastomas were treated with ATRA, the expression level of PCF11 was significantly reduced, confirming its anti-cancer effect." (PMID 33526057, 2021). "In the presence of PCF11, the GNB1 transcript with short 3’UTR is predominant in neuroblastoma differentiation." (PMID 33526057, 2021). "PCF11, as a key APA regulator, has also been recognized as responsible for the extensive 3’end alterations observed in neuroblastomas." (PMID 33526057, 2021).
neuroblastoma (continued). "Thus, although neuroblastomas derive from sympathetic nervous system precursor cells, it appears that they share neurodevelopmental features with neurons in the central nervous system with PCF11-dependent APA regulation being an important mechanism in this process." (PMID 30552333, 2018). "We identify PCF11, a CFIIm complex component involved in transcription termination and RNA 3′end maturation, as a critical regulator pervasively directing APA of hundreds of transcripts in neuroblastoma." (PMID 30552333, 2018).
prostate carcinoma (3 papers, 2022 to 2025). A carcinoma that arises from epithelial cells of the prostate gland. "Genistein, a prostate cancer preventive agent, downregulated PCF11." (PMID 35756640, 2022). "Also, PCF11 is suggested as a marker in prostate cancer, in which treatment with the prostate cancer preventive agent genistein downregulates PCF11 in LNCaP cell lines." (PMID 35756640, 2022).
colon cancer (1 paper, 2020). "NUDT21, CPSF3, CSTF2, and MTPAP were overexpressed while PCF11 and PABPN1 were suppressed in colon cancer tissues." (PMID 32153636, 2020).
latent infection (1 paper, 2023). "The expression of several factors implicated in the inhibition of viral transcription elongation, such as PCF11 (4.3-fold), GPS2 (2.6-fold), HEXIM1 (3.7-fold), and HEXIM2 (2.7-fold), was significantly upregulated in latent infection compared to actively infected cells." (PMID 38038477, 2023).
cancer (18 papers, 2007 to 2025). A tumor composed of atypical neoplastic, often pleomorphic cells that invade other tissues. "3' UTRs shortening is a hallmark of most cancer cells and that ubiquitination of PCF11 through MAGE-A11-HUWE1 ubiquitin ligase promotes 3' UTRs shortening that drives tumorigenesis." (PMID 35711821, 2022). "We found that many CPA genes are mutated in cancer, notably PCF11, WDR33, CPSF1, and SYMPK." (PMID 41463412, 2025). "Notably, we found SRSF1, HECW2, SRSF6, UBE2Z and PCF11, to be linked to carcinogenesis and cancer management 51-62 and are associated with poor prognosis in HMs." (PMID 35711821, 2022). "Based on these observations linking PCF11 to hallmark features of cancer, we hypothesised that PCF11 may determine a malignant phenotype." (PMID 30552333, 2018). "MAGE-A11-HUWE1 mediates the polyubiquitination and degradation of PCF11 to regulate APA in cancer, which supports correlation between the ubiquitin‒proteasome pathway and APA14." (PMID 38503731, 2024). "Deletion of the human PCF11 autoregulatory pA site in 4T1 metastatic cells slowed cell migration and invasion rates by 70%, suggesting a role for PCF11 in cancer development." (PMID 36315099, 2023). "PCF11 promote cancer progression via regulation of the mechanisms controlling cell proliferation, migration, and invasion." (PMID 35756640, 2022). "This is supported by observations in large-scale screens where mutations in the PCF11 promoter and 5′UTR, (which possibly can affect expression) have been identified as potential cancer drivers in multiple cancers." (PMID 32560344, 2020). "This identified 160 significant non-coding elements, including the TERT promoter, a well-known non-coding driver element, as well as elements associated with known cancer genes and regulatory genes (e.g., PAX5, TOX3, PCF11, MAPRE3)." (PMID 29354286, 2018). "We found that CPSF1 and PCF11 mutations do not predict progression-free or overall survival of cancer patients." (PMID 41463412, 2025). "MCF7-treated with Cannabidiol an anti-cancer agent significantly downregulated PCF11." (PMID 35756640, 2022). "The exact role of PCF11 in cancer development and progressing remains to be determined." (PMID 35711821, 2022). "PCF11 also appears to be involved in APA shortening in cancer." (PMID 32560344, 2020). "Our findings suggest that disruption of MAGE-A11 interaction with PCF11 may be a viable strategy to design cancer-specific therapeutics." (PMID 33004795, 2020). "Most of these APA regulators were specifically upregulated in seven cancer types, while PPP1CB, PCF11, and PABPC1 were significantly downregulated in ESCC." (PMID 35654793, 2022). "The pervasive mode of PCF11 in directing TREND suggests an important role in basic cellular programmes, including a potential function in tumorigenesis (cancer enrichment score 2.98 × 10−9)." (PMID 30552333, 2018). "On the other hand, a cancer-specific ubiquitin ligase has been shown to reduce Pcf11 levels specifically but did not alter levels of CPSF, CstF, and CFI complexes or PCF11-interacting proteins." (PMID 36761770, 2023).
tumor (8 papers, 2018 to 2023). "While high-level PCF11 determines a fatal disease progression, low levels of PCF11 instead associate with favorable outcome and spontaneous tumor regression." (PMID 35571036, 2022). "Thus, low-level PCF11 is associated with a better outcome and possibly a greater likelihood for spontaneous tumour regression." (PMID 30552333, 2018). "Ongoing in vitro experiments in our laboratory, aim to identify and validate the molecular players that link the activation of CD44, by its ligand HA, to the transcriptional regulation of PCF11 3’UTR to promote tumor cell invasion and metastasis." (PMID 35756640, 2022). "Together, these results suggest that the MAGE-A11 SBC is required for its ability to regulate PCF11, promote alternative polyadenylation and drive tumor growth." (PMID 33004795, 2020). "Notably, certain “writers” (such as ADARB2 and PCF11) with widespread frequency of CNV gain harbored decreased mRNA level in BCa compared to adjacent non-tumor tissues." (PMID 37124622, 2023). "On the other hand, CD44 was validated as a key regulator of WNT, PI3K/AKT and MAPK/ERK signaling pathways, thereby supporting our hypothesis that PCF11 is a potential novel transcriptional target that underpins CD44/HA-promoted tumor cell invasion." (PMID 35756640, 2022). "This suggests a more global role of PCF11 in coordinating the timely switch to fully committed neuronal fate thereby preventing uncontrolled embryonic proliferative programmes that may eventually give rise to neuroblastic tumours." (PMID 30552333, 2018).
PCF11 also shares sentences with these, for which no sentence is quoted: colorectal cancer (1 paper); COVID-19 (1); head and neck squamous cell carcinoma (1); hepatocellular carcinoma (1); infectious disease (1); oral squamous cell carcinoma (1).